VDR (vitamin D receptor)
Diseases named in the same sentence as VDR in open-access papers (continued):
Sharing a sentence is not in itself a finding about the gene and the disease.
rosacea (2 papers, 2016 to 2023). A chronic erythematous skin disorder that affects the face. "In the current study, our primary aim was to prospectively assess the association of serum 25OHD concentrations and VDR polymorphisms with the risk of incident rosacea among participants from the UK Biobank, aiming to fill existing knowledge gaps." (PMID 37686836, 2023). "The relationship between serum 25OHD and VDR polymorphism in other age groups and the incidence of rosacea needs further study." (PMID 37686836, 2023). "Cross-sectional studies have shown significant differences in VDR polymorphisms between rosacea patients and normal controls." (PMID 37686836, 2023). "Participants with different VDR polymorphisms had a significantly different risk of incident rosacea." (PMID 37686836, 2023). "Second, we simultaneously evaluated the influence of serum 25OHD concentration and VDR polymorphism on incident rosacea, investigated their intrinsic relationship, and stratified the most affected population." (PMID 37686836, 2023). "Specifically, a preponderance of the less active VDR allele 1 was detected, implying an association between VDR and the retinoid acid receptor pathway in rosacea." (PMID 27649161, 2016). "In patients with fulminant rosacea, an association with a BsmI polymorphism in the VDR gene has been observed." (PMID 27649161, 2016). "However, whether genetic variants in VDR alter the relationship between serum 25OHD and the risk of rosacea remains unclear." (PMID 37686836, 2023). "In addition, there is limited evidence on VDR polymorphism and rosacea pathogenesis." (PMID 37686836, 2023). "In addition, stratified analysis by sex suggested that VDR polymorphism had no sex specificity on rosacea onset after multivariate adjustment." (PMID 37686836, 2023).
seborrhea (2 papers, 2021 to 2024). "Considering the role of inflammatory cascade in the pathogenesis of seborrheic dermatitis and the inhibitory effect of VDR and vitamin D on immune system, vitamin D deficiency can be suggested as a risk factor for developing seborrheic dermatitis." (PMID 33688341, 2021).
sepsis syndrome (2 papers, 2009 to 2023). "Since many cells of the immune system possess the vitamin D receptor, vitamin D status may prove to be an important factor in management of sepsis syndrome and other critical illness." (PMID 19389235, 2009).
skin atrophy (2 papers, 2014 to 2024). The degeneration and thinning of the epidermis and dermis. "In contrast, studies mostly performed in mice suggest that vitamin D receptor (VDR) agonists have opposing effects on many of the cellular and molecular mechanisms underlying glucocorticoid-induced skin atrophy, including effects on cell proliferation, epidermal lipids and antimicrobial peptides." (PMID 25027750, 2014). "Previous studies in hairless mice have suggested that vitamin D receptor agonists may counteract glucocorticoid-induced skin atrophy and induce collagen synthesis." (PMID 25027750, 2014).
sleep disorder (2 papers, 2023 to 2024). A change from the patient's baseline sleeping pattern, in the hours slept and/or an alteration/dysfunction in the stages of sleep. "Only two small studies have investigated the role of VDR polymorphisms in other sleep disorders." (PMID 38584183, 2024).
spinal tuberculosis (2 papers, 2022 to 2025). "The severity of spinal tuberculosis had been reported to be associated with vitamin D receptor (VDR), osteopontin (OPN), and bone morphogenetic protein-4 (BMP-4) gene polymorphism." (PMID 35633888, 2022). "VDR was associated with the clinical severity of spinal tuberculosis." (PMID 35633888, 2022). "Immunofluorescence staining of TUNEL and VDR was conducted, showing strong positive signals in patients with spinal tuberculosis compared to healthy controls." (PMID 40396181, 2025).
T cell lymphoma (2 papers, 2017 to 2022). "Gene expression profiling of PEL cells have demonstrated that VDR is highly expressed in PEL cells as compared to normal B and T cell lymphoma and their sensitivity to vitamin D analogue EB1089, implicates a role for VDR in KSHV pathogenesis." (PMID 28963501, 2017).
Vertigo (2 papers, 2020 to 2025). An abnormal sensation of spinning while the body is actually stationary. "Moreover, VDR is expressed in the saccule, utricle, and semicircular canal duct, with VDR deficiency found to induce vertigo." (PMID 32731479, 2020).
ZIKV infection (2 papers, 2024 to 2025). "The results show that ZIKV infection suppresses the expression of VDR, CYP24A1, and CAMP in monocytes, suggesting an alteration of the VitD3 signaling pathway." (PMID 38839691, 2024). "The effect of ZIKV infection on the VitD3 system of monocytes was investigated by determining the relative levels of expression of VDR, CYP24A1, and CAMP mRNA by RT-qPCR." (PMID 38839691, 2024). "However, ZIKV infection has been shown to inhibit the expression of VDR target genes in human monocytes, thereby preventing Vitamin D antiviral effects." (PMID 40839599, 2025). "The observed downregulation of CYP24A1 during ZIKV infection may further indicate specific viral interference with VDR gene expression." (PMID 38839691, 2024). "We found that ZIKV infection leads to decreased VDR mRNA expression." (PMID 38839691, 2024). "Mechanistically, several signaling pathways may be involved in the inhibition of VDR expression following ZIKV infection, and further work is necessary to determine the mechanism by which ZIKV inhibits VitD3 signaling through decreased VDR transcription." (PMID 38839691, 2024). "The results showed a significant decrease in the expression of vitamin D3 receptor (VDR), cytochrome P450 family 24 subfamily A member 1 (CYP24A1), and cathelicidin antimicrobial peptide (CAMP) genes upon ZIKV infection." (PMID 38839691, 2024). "Thus, a potential explanation for the inhibition of VDR and CAMP mRNA expression by ZIKV infection could involve the expression of innate immune receptors, such as TLR7 and TLR8, that recognize intracellular viral RNA." (PMID 38839691, 2024).
Acetabular dysplasia (1 paper, 2017). A smaller than normal acetabulum that has insufficient femoral head coverage leading to abnormal hip joint contact pressures, instability and pain. "Vitamin D plays a role in DDH, as humans with homozygosity for the mutant Taq1 vitamin D receptor t allele demonstrate increased acetabular dysplasia." (PMID 28386583, 2017).
acute GVHD (1 paper, 2018). "Receptors with aa genotype and high VDR activity showed a trend toward a higher risk of acute GVHD, although differences were not statistically significant." (PMID 30205552, 2018).
adrenal carcinoma (1 paper, 2015). A carcinoma involving a adrenal gland. "Downregulation of VDR gene expression in adrenal carcinomas may result from epigenetic events, that is, methylation of cytosine nucleotides in CpG island of VDR promoter." (PMID 26843863, 2015). "The VDR promoter methylation might be a target for pharmacological agents to treat adrenal cancer in selected cases." (PMID 26843863, 2015).
adrenal hypoplasia (1 paper, 2015). "Included in this group were AR, Coup-TFα, Coup-TFβ, dosage-sensitive sex reversal-adrenal hypoplasia congenital critical region on the X chromosome, gene 1 (DAX1), ERα, ERRα, HNF4γ, liver receptor homolog-1 (LRH1), NOR1, NURR1, PPARγ, RARβ, RORα, RORβ, and VDR." (PMID 26244663, 2015).
adrenal tumors (1 paper, 2015). "qPCR analysis demonstrated variable levels of VDR mRNA in all adrenal tumors, with VDRmRNA expressed at higher levels in ACAs than in ACCs (0.41 ± 0.2 versus 0.11 ± 0.08 arbitrary units, P < 0.01)." (PMID 26843863, 2015).
age-related macular degeneration (1 paper, 2022). Age-related loss of vision in the central portion of the retina (macula), secondary to retinal degeneration. "Stimulation of the VDR in respective tissues results in reduced inflammation in dry eye disease, age-related macular degeneration (AMD), inhibition of retinal neovascularization, protection of RPE cells from oxidative damage and reduction of corneal wound scarring." (PMID 38983544, 2022).
airway hyperresponsiveness (1 paper, 2025). "It reduces eosinophilic inflammation and airway hyperresponsiveness by binding to the vitamin D receptor (VDR) expressed on immune cells, which in turn stimulates the differentiation of regulatory T cells and inhibits pro-inflammatory Th2 and Th17 responses." (PMID 40751233, 2025).
alcohol abuse (1 paper, 2018). The use of alcoholic beverages to excess, either on individual occasions ("binge drinking") or as a regular practice. "At the Bsm-1 (rs1544410) VDR gene polymorphic site the frequency of the alleles, B and b, were determined in our study’s alcohol-abuse controls and in those diagnosed with AP." (PMID 29966312, 2018). "Here, we used SNP analysis to identify differences in the frequency of Apa-1, Taq-1, Bsm-1, and Fok-1 genotypes/alleles in the VDR gene between AP and alcohol-abuse patients." (PMID 29966312, 2018).
Aminoaciduria (1 paper, 2025). An increased concentration of an amino acid in the urine. "Aminoaciduria is also observed in genetic conditions involving vitamin D metabolism and action, such as defects in 1-α-hydroxylase and VDR." (PMID 40225330, 2025).
ampullary cancer (1 paper, 2021). "Our analysis demonstrated that PPAR and lipid metabolism-related pathways, such as “Regulation of lipid metabolism PPAR regulation of lipid metabolism” and “Regulation of lipid metabolism RXR-dependent regulation of lipid metabolism via PPAR, RAR, and VDR” were important in ampullary cancer." (PMID 33390794, 2021).
and phosphorus metabolism disorder (1 paper, 2024). "A randomized double-blind crossover trial suggested that Par may cause calcium and phosphorus metabolism disorder after long-term medication, but this problem exists commonly in the clinical application of VDR agonists." (PMID 37991543, 2024).
apical periodontitis (1 paper, 2021). "Recently, the association between polymorphisms in genes encoding estrogen receptors 1 and 2 (ESR1 and ESR2), vitamin D receptor (VDR), and in miRNA-17 with apical periodontitis was reported in the literature." (PMID 33886945, 2021).
arterial diseases (1 paper, 2024). "Due to its broad distribution in vascular endothelial cells, vascular smooth muscle cells, and cardiomyocytes, the role of VDR in arterial diseases has received extensive attention." (PMID 39519451, 2024).
Arterial thrombosis (1 paper, 2022). The formation of a blood clot inside an artery. "Decreased expression of VDR is correlated with arterial thrombosis and as per previous reports." (PMID 35645372, 2022).
behavioral disorders (1 paper, 2010). "All together, these properties could stabilize the neurophysiologic function and explain why the lack of functional VDR in the brain of VDR-knockout transgenic mice models was responsible for behavioral disorders due not only to an increased level of stress but also to severe motor disorders." (PMID 20937091, 2010).
brain cancer (1 paper, 2013). A primary or metastatic malignant neoplasm affecting the brain. "The aim of this study was to evaluate the association between polymorphisms in the VDR Fok-I and Taq-I and the risk of brain cancer in Turkish patients." (PMID 23691496, 2013). "Despite an extensive literature study, there was no study that reported the relationship between VDR polymorphisms and brain cancer susceptibility." (PMID 23691496, 2013).
Cachexia (1 paper, 2017). Severe weight loss, wasting of muscle, loss of appetite, and general debility related to a chronic disease. "This in vivo observation, coupled with the results obtained in vitro, suggests that VDR might play a role in the onset and/or progression of cachexia." (PMID 28423519, 2017).
calcium metabolism disorder (1 paper, 2020). "Moreover, the patient with a calcium metabolism disorder had a variant of uncertain significance in the VDR gene." (PMID 32997713, 2020).
cervical squamous cell carcinoma (1 paper, 2024). A squamous cell carcinoma arising from the cervical epithelium. "The role of the VDR in shaping the tumor microenvironment and influencing immune responses in cervical squamous cell carcinoma has received significant attention." (PMID 39268267, 2024). "In cervical squamous cell carcinoma, we observed that the VDR gene was altered in 1.68% of 297 cases." (PMID 39268267, 2024). "Vitamin D receptor (VDR), specifically the 1,25-dihydroxy form, holds significant importance in various types of cancer, including cervical squamous cell carcinoma (CESC), which poses a significant public health challenge." (PMID 39268267, 2024). "VDR: vitamin D (1,25-dihydroxy vitamin D3) receptor gene; Coef: coefficient; CESC: cervical squamous cell carcinoma; HR: hazard ratio; 95%CI_l: lower 95% confidential interval; 95%CI_u: upper 95% confidential interval; sig: significance, p: p-value." (PMID 39268267, 2024). "The expression of the VDR in CESC was validated using samples from 5 patients with normal cervical epithelium and 11 cases of cervical squamous cell carcinoma." (PMID 39268267, 2024).
cervical tumours (1 paper, 2023). "In summary, VDR expression is upregulated in cervical tumours; however, a negative feedback loop regulating autocrine vitamin D signalling via attenuated VDR expression, especially at a supraphysiological 25(OH)D3 dose, is likely to be operable in SiHa cells." (PMID 36979850, 2023).
childhood cancers (1 paper, 2022). "In this study, lower vitamin D receptor (VDR) expression was associated with a worse prognosis in various childhood cancer patients (significant correlation, p = 0.0061)." (PMID 35884356, 2022). "In conclusion, VDR expression measured by IHC staining is inversely associated with aggressive characteristics in different childhood cancers." (PMID 35884356, 2022). "The downregulation of VDR expression in more aggressive childhood cancers suggests that functional vitamin D activity may slow or block cancer progression." (PMID 35884356, 2022). "The identification of VDR status in various childhood cancers has highlighted potential patient populations that could benefit from the newly identified biomarker." (PMID 35884356, 2022).
chlamydial infection (1 paper, 2025). "In VDR-deficient (VDR-/-) mouse models of chlamydial infection, bacterial clearance was impaired compared to wild-type mice." (PMID 40558546, 2025).
cholesteatoma (1 paper, 2023). A pathologic process characterized by the proliferation of keratinizing squamous epithelium resulting in the accumulation of keratin and cells in the middle ear and/or mastoid. "Moreover, since a high dose calcium diet prevented hypomineralization of auditory ossicles in vitamin D receptor deficient mice, modulation of calcium homeostasis might also be effective as an additive measure to improve bone mineralization of ossicles in cholesteatoma." (PMID 37872266, 2023).
chronic hepatitis (1 paper, 2022). An active inflammatory process affecting the liver for more than six months. "Our study identified the association between two distinct phases, VDR polymorphisms and HBV inactive carrier (IC) and chronic hepatitis (CH)." (PMID 36490235, 2022). "Allele and genotype frequencies of VDR SNPs in HBV inactive carrier and chronic hepatitis phases." (PMID 36490235, 2022). "Haplotype frequencies of VDR SNPs in HBV inactive carrier and chronic hepatitis phases." (PMID 36490235, 2022).
colon polyp (1 paper, 2011). "Thirdly, the study assessed whether polymorphisms in the VDR gene are also polymorphic in the AA population at HUH and if so, whether any of them are associated with colon polyp." (PMID 22022386, 2011). "Consequently, we evaluated serum 25(OH) D levels, vitamin D receptor (VDR) polymorphisms and the methylation status of the tumor suppressor gene dickkopf homolog 1 (DKK1) as risk factors for colon polyp in this population." (PMID 22022386, 2011). "Moreover, none of the comprehensive tagging SNPs in VDR were significantly associated with colonic polyps." (PMID 22022386, 2011).
deafness (1 paper, 2022). An inherited or acquired condition characterized by the complete loss of the ability to hear from one or both ears. "After binding with other transcription factors, VDR interacts with vitamin D-responsive elements and up- or down-regulates hundreds of genes directly controlled by vitamin D. In the mouse inner ear, mutations in the VDR gene can cause progressive deafness." (PMID 36497006, 2022).
demyelinating disease (1 paper, 2020). A broad group of disorders that affect the myelin sheaths that cover the neurons. "A study is already hypothesizing VDR-activating drugs may be able to enhance remyelination in MS patients and other demyelinating diseases which may possibly include NMO." (PMID 32373353, 2020).
dental fluorosis (1 paper, 2024). A condition that results from excessive fluoride ingestion during tooth development, resulting in tooth discoloration ranging from white streaks to brown stains and cracks or pits in the tooth enamel. "Considering the potential role of VDR and PTH in amelogenesis, as well as the limited evidence about the association between DDE and these genes, this cross-sectional study aimed to investigate the association between DDE (excluding dental fluorosis) and SNPs in the genes encoding VDR and PTH." (PMID 38922252, 2024).
dermatomyositis (1 paper, 2015). Dermatomyositis (DM) is a type of idiopathic inflammatory myopathy characterized by evocative skin lesions and symmetrical proximal muscle weakness. "We studied VDR-BsmI, VDR-ApaI, VDR-TaqI, and VDR-FokI polymorphisms and haplotypes in 89 Hungarian poly-/dermatomyositis patients (69 females) and 93 controls (52 females)." (PMID 25649962, 2015).
dysplasia (1 paper, 2024). A usually neoplastic transformation of the cell, associated with altered architectural tissue patterns. "In our study, both oral dysplasia cells and oral explants from OPMD patients with histological diagnosis of dysplasia showed decreased nuclear expression of VDR." (PMID 38666921, 2024).
E. coli infection (1 paper, 2017). "Next, we investigated the effect of E. coli infection on VDR in human bladder cells." (PMID 28749951, 2017). "Furthermore, we show that the vitamin D receptor was upregulated in the urinary bladder and translocated into the cell nucleus after E. coli infection." (PMID 28749951, 2017). "Only the uroepithelium was affected, suggesting a local VDR response to E. coli infection." (PMID 28749951, 2017).
edema (1 paper, 2022). An abnormal accumulation of fluid beneath the skin, or in one or more cavities of the body. "Finally, carriers of the VDR rs731236 TC genotype had decreased odds for development of peripheral edema (OR = 0.43; 95% CI = 0.20–0.90; p = 0.026)." (PMID 35517045, 2022).
embryonal carcinoma (1 paper, 2023). A non-seminomatous malignant germ cell tumor characterized by the presence of large germ cells with abundant cytoplasm resembling epithelial cells, geographic necrosis, high mitotic activity, and pseudoglandular and pseudopapillary structures formation. "Another in vitro study of VDR expression confirmed high nuclear and cytoplasmic staining in an embryonal carcinoma cell line, where VDR was inducible with the addition of Vitamin D but downregulated through testosterone." (PMID 37242266, 2023). "As opposed to GCNIS, expression of VDR and Vitamin D-metabolizing enzymes was non-existent or low for embryonal carcinoma (EC) cells, implying that this pathway was deactivated during the shift from GCNIS to EC." (PMID 37242266, 2023).
enamel hypoplasia (1 paper, 2024). "In this study, enamel hypoplasia, MIH/HSPM, and non-MIH/HSPM demarcated opacities were grouped as the main phenotype “DDE” once the hypothesis raised here is that the candidate genes VDR and PTH are involved in DDE regardless of the subphenotype." (PMID 38922252, 2024).